LPL (lipoprotein lipase)
Diseases named in the same sentence as LPL in open-access papers (continued):
Sharing a sentence is not in itself a finding about the gene and the disease.
atrial fibrillation (1 paper, 2024). A disorder characterized by an electrocardiographic finding of a supraventricular arrhythmia characterized by the replacement of consistent P waves by rapid oscillations or fibrillatory waves that vary in size, shape and timing and are accompanied by an irregular ventricular response. "The aim of the study was to examine the expression profile of genes (APOE, FTO, and LPL) associated with metabolic syndrome (MetS) in subjects with concomitant atrial fibrillation (AF)." (PMID 39166676, 2024). "Correlation analysis of gene expression of APOE, FTO, and LPL genes with the clinical parameters of atrial fibrillation in studied groups." (PMID 39166676, 2024).
bladder cancers (1 paper, 2023). "Lipid-lowering LPL variants were associated with decreased risks of bladder cancers (OR 0.56; 95% CI: 0.39 to 0.79; p-IVW=1.06×10-3, FDR=5.94×10-3)." (PMID 38127052, 2023).
brain cancer (1 paper, 2023). A primary or metastatic malignant neoplasm affecting the brain. "Another interesting target identified was the TSPO -(Translocator protein) that is known to be expressed exclusively in brain cancers, including GBM, and can be used for delivering drugs across the blood brain barrier along with DNA topoisomerase I (TOP1), Lipoprotein Lipase (LPL), and DNMT1." (PMID 37637064, 2023).
cervical cancer (1 paper, 2023). A primary or metastatic malignant neoplasm involving the cervix. "LPL also had one of the highest FC; it was upregulated in cervical squamous cell carcinoma, and their overexpression in the cervical cancer cell lines SW756 and C-33 A increased their invasiveness of them." (PMID 36992411, 2023).
Cholestatic liver disease (1 paper, 2022). "ApoA-I and apoA-II, major apolipoproteins that are carried by HDL, have been described to be decreased in cholestatic liver diseases together with impaired HL, lipoprotein lipase (LPL), and LCAT activities." (PMID 35268313, 2022).
chronic hepatitis (1 paper, 2019). An active inflammatory process affecting the liver for more than six months. "LPL is the key enzyme of lipid metabolism, which is positively correlated with the miR-122 expression in chronic hepatitis." (PMID 31398934, 2019).
colorectal tumors (1 paper, 2024). "Another two macrophage clusters with a lipid-associated (LA) metabolism transcriptional signature, including genes such as FABP5, LPL, and LIPA, named RTM_LA (n = 3569) and Mac_LA (n = 1249), were found enriched in breast, lung, and colorectal tumors." (PMID 38972873, 2024).
demyelination (1 paper, 2018). "Using the EAE model of demyelination we showed that LPL activity in the brain is significantly increased at 30 days following immunization." (PMID 29599706, 2018).
endometrial cancer (1 paper, 2023). Primary or metastatic malignant neoplasm involving the endometrium (mucous membrane that lines the endometrial cavity). "One hypothesis is that HC tracks with gluteofemoral fat accumulation, which is associated with a more favourable adipokine profile and increased lipoprotein lipase activity, profiles that have been linked to lower endometrial cancer risk." (PMID 36460776, 2023).
familial hypobetalipoproteinemia (1 paper, 2024). "ANGPTL3 was initially identified from familial hypobetalipoproteinemia in humans due to its role as an inhibitor of both lipoprotein lipase and endothelial lipase." (PMID 38462608, 2024).
fibrosis (1 paper, 2024). the formation of excess fibrous connective tissue in an organ or tissue in a reparative or reactive process. "The loss of LPL-derived fatty acids in LPL-deficient mice leads to increased glucose metabolism in the heart, cardiac contractile dysfunction and increased cardiac fibrosis." (PMID 38392646, 2024).
Flavivirus Infections (1 paper, 2020). Infections with viruses of the genus FLAVIVIRUS, family FLAVIVIRIDAE. "Proteins differentially expressed in flavivirus infections other than Zika include SLC3A2, PODXL, ASNS and LPL." (PMID 32873194, 2020).
gastric tumors (1 paper, 2017). "We found that LDL and HDL import through their receptors via an outside-in cholesterol-shuffling route, and then cholesterol is unloaded by LPL (L/R route) into gastric tumors." (PMID 27893427, 2017).
glioblastoma (1 paper, 2024). The most malignant astrocytic tumor (WHO grade IV). "However, in glioblastoma cells, αvβ3 interaction with the ECM protein osteopontin promotes aerobic glycolysis, and β3 knockout mice have a higher serum triglyceride level caused by disrupted lipoprotein lipase secretion." (PMID 38933087, 2024).
Glomerular disease (1 paper, 2025). "Glomerular disease associated with nephrotic range proteinuria carries an additional risk of elevated LDL-C levels owing to impaired clearance of lipoproteins as a result of decreased hepatic and peripheral lipoprotein lipase and increased cholesterol biosynthesis." (PMID 39940317, 2025).
glycogen storage disease type 1a (1 paper, 2023).
HCMV infection (1 paper, 2017).
helminth infection (1 paper, 2025). "Helminth infection also significantly lowered the lipid accumulation in liver, which may attribute to the significant up-regulated expression levels of apolipoprotein E (ApoE) and down-regulated expression of peroxisome proliferator-activated receptor-gamma (PPAR-γ) and lipoprotein lipase (LPL)." (PMID 40708918, 2025).
hemophagocytic lymphohistiocytosis (1 paper, 2024). "Hypothesized mechanisms include hemophagocytic lymphohistiocytosis (HLH) syndrome and acquired lipoprotein lipase (LPL) inhibitors." (PMID 38979030, 2024).
hemorrhagic stroke (1 paper, 2023). A stroke caused by a bleed on the brain. "Recent evidence supports the association between LPL-Hind III polymorphism and both hemorrhagic stroke risk and high lipid levels in the Chinese Han population." (PMID 37954769, 2023).
Hip dysplasia (1 paper, 2021). The presence of developmental dysplasia of the hip. "Nine studies reported the measured values in healthy dogs; however, 20 studies investigated dogs with and without different orthopedic diseases, such as CrCL rupture, different grades of MPL or LPL, and other orthopedic diseases such as hip dysplasia." (PMID 34204283, 2021).
hypoadiponectinemia (1 paper, 2025). "Nonetheless, hypoadiponectinemia has been linked with lower size of low-density lipoprotein (LDL), decreased HDL and lipoprotein lipase (LPL) activity, and higher levels of triglycerides." (PMID 40563460, 2025).
Immunodeficiency (1 paper, 2021). Failure of the immune system to protect the body adequately from infection, due to the absence or insufficiency of some component process or substance. "So far, only one LPL case with immunodeficiency has been reported in the neonatal period." (PMID 34544385, 2021).
infarction (1 paper, 2022). A localised pathological necrosis of tissue resulting from obstruction of the blood supply usually by a thrombus, an embolus, or vascular torsion. "The markers LPL, M-CSF, and ADAM8 were also consistently expressed by F4/80+ cells within the infarction core." (PMID 35177618, 2022). "Also, the density of LPL+, M-CSF+, and ADAM8+ cells increased and spread from the infarction core to the cerebral cortex, confirming expression of the top SAMC markers in ischemic brain parenchyma." (PMID 35177618, 2022).
intestinal tumour (1 paper, 2017). "As GLUTag cells were originally derived from an intestinal tumour, it is conceivable that their high expression of LPL may reflect a cancerous phenotype." (PMID 28866808, 2017).
invasive breast carcinoma (1 paper, 2024). A carcinoma that infiltrates the breast parenchyma. "For the five genes (LPL, PCK1, KRT6B, SFRP2, SHC2) that were differentially expressed between the datasets, we analyzed the alterations in metastatic breast cancer and invasive breast cancer genetic profiles." (PMID 38791477, 2024).
keloid (1 paper, 2022). An irregularly shaped, elevated mark on the skin caused by deposits of excessive amounts of collagen during wound healing. "PPARGC1A, PPARG, PLIN1, LPL, ABHD5, lncRNA PART1, lncRNA ENTPD3-AS1 in trunk keloid and DGAT2 in ear keloid showed decreased trend under paired comparation." (PMID 35677827, 2022).
Knobloch syndrome (1 paper, 2023). "Knobloch syndrome patients carrying a null mutation of COL18A have increased serum triglyceride levels after fasting and show reduced activity and mass of plasma lipoprotein lipase (LPL), which cleaves fatty acids from circulating lipoproteins." (PMID 37239083, 2023).
lactic acidosis (1 paper, 2023). Metabolic acidosis characterized by the accumulation of lactate in the body. "Pre-prandial lactic acidosis is not part of the clinical spectrum in LPL deficiency, but it is obligatory in GSD1a deficiency." (PMID 37630727, 2023).
large-cell lung cancer (1 paper, 2025). "At the same time, we also observed the inhibitory effect of activating LPL on H1299 cells, suggesting that LPL may also play an important role in large-cell lung cancer." (PMID 40427755, 2025). "Additionally, we observed that treatment with Ibrolipim could also significantly inhibit the cell viability and migration ability of H1299 cells, suggesting that LPL may also have certain value in large-cell lung cancer." (PMID 40427755, 2025).
leukemia (1 paper, 2021). A malignant (clonal) hematologic disorder, involving hematopoietic stem cells and characterized by the presence of primitive or atypical myeloid or lymphoid cells in the bone marrow and the blood. "Among the metabolic genes downregulated in NPM1/cohesin-mut compared with NPM1-mut AML, CHST13, ADCY9, PRR16, LPL, and SLC1A3 were confirmed by STAG2-deficient model of NPM1-mut leukemia." (PMID 34193978, 2021).
limb-girdle muscular dystrophy (1 paper, 2014). Limb-girdle muscular dystrophy (LGMD) is a heterogeneous group of muscular dystrophies characterized by proximal weakness affecting the pelvic and shoulder girdles. "When targeting the muscle in humans, T-cell responses directed to the capsid antigen were documented in AAT-deficient subjects receiving intra-muscular injection of an AAV1–AAT vector, in study on AAV1-α-sarcoglycan in limb-girdle muscular dystrophy subjects and in our own LPL-deficient subjects." (PMID 24624131, 2014).
lung adenocarcinoma (1 paper, 2025). A carcinoma that arises from the lung and is characterized by the presence of malignant glandular epithelial cells. "Lipoprotein lipase (LPL) is a key enzyme in lipid metabolism that hydrolyzes triglycerides, but its role in lung adenocarcinoma (LUAD) has not received much attention or research." (PMID 40427755, 2025).
mastitis (1 paper, 2017). Inflammation of breast tissue during lactation or postpartum due to an obstructed duct or infection. "The expression of FASN was negatively affected by mastitis, whereas TZD treatment prevented a decrease in expression of FASN but delayed the increase in expression of LPL in mastitis-treated goats after IMI." (PMID 28740504, 2017).
monocytic leukemia (1 paper, 2024). "The deletion or mutation of the CT element required for the binding of transcription factors SP1 and SP3 in the human lipoprotein LPL promoter led to a reduction of about 70–80% in promoter activity in a human monocytic leukemia cell line." (PMID 39590382, 2024).
mood disorder (1 paper, 2025). A cognitive disorder a disturbance in which the person's mood is hypothesized to be the main underlying feature. "Furthermore, lincRNAs like LINC02713 may correlate with mood disorders, and genes related to lipid metabolism, such as LPL, connect to mood regulation." (PMID 40125487, 2025).
motor neuron disease (1 paper, 2021). "In contrast with these data suggesting increased TG synthesis, lipoprotein lipase is upregulated in the symptomatic stage of the G93A mice model of motor neuron disease." (PMID 34396104, 2021).
myeloma (1 paper, 2022). "The LPL patient presented both PC and B-cell aberration with FC positivity in CD19 and CD45 in BM PCs, indicative of a histologically lymphoplasmacytic myeloma phenotype." (PMID 36362214, 2022).
Myocardial fibrosis (1 paper, 2024). "Previous studies have suggested that the protective effect of LPL agonists on AF may be linked to chronic inflammation and myocardial fibrosis, while FGF5 may increase the risk of AF through myocardial fibrosis and structural remodeling of the atrium." (PMID 39563941, 2024).
myocardial ischemia (1 paper, 2017). A disorder of cardiac function caused by insufficient blood flow to the muscle tissue of the heart. "Glycyrrhizic acid also exhibits cardioprotective effects against isoproterenol-induced myocardial ischemia in rats and improves lipoprotein lipase expression, insulin sensitivity, serum lipid, and lipid deposition in high-fat diet-induced obese rats." (PMID 28099940, 2017).
obstructive sleep apnea (1 paper, 2016). "Animal studies show that acute hypoxia, a model of obstructive sleep apnea, reduces adipose tissue lipoprotein lipase activity and increases non-esterified fatty acid release, adversely affecting postprandial lipemia." (PMID 27421877, 2016).
osteonecrosis (1 paper, 2025). A none disease characterized by death of bone tissue due to a lack of blood supply.
phlebitis (1 paper, 2019). Inflammation of a vein. "In addition, the LPL mRNA signal in affected chickens was enhanced in the endothelium of veins undergoing phlebitis, often characterized by intramural infiltrates as well as perivascular cuffing comprising primarily lymphocytic cells and to a lesser extent, macrophages." (PMID 31748687, 2019).
psychosis (1 paper, 2025). "The proposed pathways include enhanced lipoprotein lipase activity and β oxidation, though inflammation and oxidative stress, which are hallmarks of psychosis, may blunt these adaptations." (PMID 40677207, 2025).
pulmonary obstruction (1 paper, 2024). "Another proposal is the chemical theory where bone marrow fats are released via lipoprotein lipase in a pro-inflammatory state, resulting in vascular/pulmonary obstruction." (PMID 37133760, 2024).
renal fibrosis (1 paper, 2024). A final common manifestation of a wide variety of chronic kidney diseases characterized by glomerulosclerosis and tubulointerstitial fibrosis. "However, while chemical inhibition of LPL in diabetic mice caused an elevation in plasma TGs, it did not alter renal fibrosis, suggesting that LPL is not a key molecule in the development of diabetic kidney fibrosis." (PMID 39630889, 2024).
Sjögren’s syndrome (1 paper, 2020). "Subsequently reports of autoimmune hyperlipidemia have been described in patients with lupus erythematosus and Sjögren’s syndrome and in several cases antibodies to LPL were identified." (PMID 33193106, 2020). "More recently 6 cases with CS were found to have antibodies to GPIHBP1, four of whom had either lupus or Sjögren’s syndrome attesting to the importance of this protein for LPL activity." (PMID 33193106, 2020).
sleep apnea syndrome (1 paper, 2024). A disorder characterized by multiple cessations of respirations during sleep that induce partial arousals and interfere with the maintenance of sleep. "LPL, that lowered serum TG levels, was positively associated with the risk of sleep apnea syndrome (OR = 1.193; 95% CI = 1.101–1.294; P = 1.77E−05)." (PMID 39470521, 2024). "However, LPL-based lipid-lowering drugs may increase the risk of sleep apnea syndrome." (PMID 39470521, 2024).
stenosis (1 paper, 2016). "Quince leaf extract successfully reduced level of total cholesterol (TC), low density lipoproteins (LDL), serum triglycerides (TG), liver stenosis and increased high density lipoproteins (HDL) and lipoprotein lipase (LPL)." (PMID 27445806, 2016).
Takayasu arteritis (1 paper, 2009). A rare inflammatory large-vessel vasculitis primarily affecting the aorta and its major branches, but also other large vessels, causing stenosis, occlusion, or aneurysm. "Since lipoprotein lipase is localized on endothelial surface of all vascular system carrying out triglycerides hydrolysis, it is therefore reasonable to speculate that the lipoprotein lipase may be involved in the inflammatory vascular process of Takayasu's arteritis." (PMID 19606253, 2009). "Results from the current study showed that patients with Takayasu's arteritis do not present antibodies to lipoprotein lipase, although about seventy percent of them had at least one lipid risk levels for cardiovascular disease." (PMID 19606253, 2009).
tendinopathies (1 paper, 2024). "This inhibition of inflammation may be a key mechanism through which LPL treats tendinopathies." (PMID 39286458, 2024).
Thrombocytopenia (1 paper, 2023). A reduction in the number of circulating thrombocytes. "Fluctuations in the PLC and thrombocytopenia is part of the natural history of FCS (HoLPL) and has also been observed in a lesser extent among patients with partial LPL deficiency (HeLPL)." (PMID 37370069, 2023).
thromboembolic diseases (1 paper, 2019). "Results for apolipoprotein C3 (APOC3) and lipoprotein lipase (LPL) followed a pattern more similar to the analysis for triglycerides, showing inverse associations with thromboembolic diseases (P=0.007 for APOC3, P=0.089 for LPL for any venous thromboembolism)." (PMID 31756303, 2019).
thrombophilia (1 paper, 2024). A condition characterized by an abnormally high level of thrombi. "No thrombophilia-related gene mutation was detected, but a heterozygous mutation in lipoprotein lipase (LPL) gene was identified." (PMID 38975277, 2024).
thymic lymphomas (1 paper, 2015). "The results from microarray-base gene expression analysis showing the down-regulation of LPL and FABP4 in mice with radiation-induced thymic lymphomas hinted at the involvement of these unknown immunosuppressive factors in thymic lymphomas pathogenesis." (PMID 25923834, 2015). "The levels of LPL and FABP4, both of which are involved in lipid uptake and metabolism, was down-regulated in the thymus, spleen and PBMC of mice with thymic lymphomas, compared to the levels in mice that did not receive radiation treatment." (PMID 25923834, 2015).
toxoplasmosis (1 paper, 2014). A parasitic disease contracted by the ingestion or fetal transmission of toxoplasma gondii. "It is a major determinant of infection-induced hypertriglyceridemia, by modulating adipose and muscle lipoprotein lipase activity in toxoplasmosis." (PMID 25530920, 2014). "Toxoplasma organisms may modulate weight gain by decreasing muscle lipoprotein lipase and altering tissue lipoprotein lipase activity during chronic toxoplasmosis to elevate triglyceride distribution in the adipose tissues." (PMID 25530920, 2014).
type V hyperlipidemia (1 paper, 2014). "Surprisingly, LPL activity has been poorly documented in heterozygous LPL mutation carriers with a history of type V hyperlipidemia." (PMID 24788417, 2014).